CHD7 (chromodomain helicase DNA binding protein 7)
Diseases named in the same sentence as CHD7 in open-access papers (continued):
Sharing a sentence is not in itself a finding about the gene and the disease.
CHARGE syndrome (continued). "A second example of a disease involving defective chromatin remodeling is CHARGE syndrome, which is caused by heterozygous mutations in the gene encoding CHD7." (PMID 26188466, 2016). "In the case of DSD04, the phenotype resembles that of CHARGE syndrome, so it is very likely that the novel deletion in CHD7 is the causative mutation." (PMID 26980296, 2016). "Another condition associated with various cardiac malformations is CHARGE syndrome, which, in most cases, is caused by heterozygous mutations or deletions of the chromodomain helicase DNA-binding protein 7 (CHD7)." (PMID 29367567, 2016). "Two thirds of CHARGE syndrome cases are caused by mutations in the chromatin-organizing protein chromodomain helicase DNA-binding gene 7 (CHD7; called Kismet in Drosophila)." (PMID 26935104, 2016). "Mutations in MLL2 and KDM6A are also implicated in Kabuki syndrome, whilst mutations in CHD7 are implicated in CHARGE syndrome." (PMID 26188466, 2016). "The present patient shows that deletion of region upstream of CHD7 gene is sufficient per se to cause CHARGE syndrome." (PMID 26334530, 2015). "Despite most patients carrying mutations in CHD7, it is still possible that other genes are involved in CHARGE syndrome." (PMID 26411921, 2015). "Pathogenic CHD7 variants were detected in two patients with clinical features consistent with CHARGE syndrome." (PMID 26666243, 2015). "CHARGE syndrome is caused by spontaneous loss-of-function mutations to the ATP-dependant chromatin remodeller chromodomain-helicase-DNA-binding protein 7 (CHD7)." (PMID 26102480, 2015). "These important in vitro studies suggest that most CHD7 mutations found in CHARGE syndrome affect ATP-dependent chromatin remodelling activity." (PMID 26411921, 2015). "In a routine clinical setting, sequencing of CHD7 reveals a mutation in 32–41% of the patients suspected of having CHARGE syndrome." (PMID 26411921, 2015). "Recent work has shown that the BAF complex orchestrates the development of neural crest cells via co-operating with CHD7, which is mutated in the majority of CHARGE syndrome cases." (PMID 26553192, 2015). "In 2004, shortly before the next-generation sequencing era, mutations in the CHD7 gene (MIM 608892) were identified in patients with CHARGE syndrome." (PMID 26411921, 2015). "In patients with clinically typical CHARGE syndrome, the detection rate of CHD7 mutations is over 90%." (PMID 26411921, 2015). "Since the first identification of CHD7 mutations in patients with CHARGE syndrome just over 10 years ago, clinical genetic, animal, and biochemical studies have led to important insights into the causes of CHARGE syndrome phenotypes." (PMID 26411921, 2015). "Given that up to 17% of patients with a CHD7 mutation do not fulfil these strict diagnostic criteria, molecular genetic testing of CHD7 is important to confirm a diagnosis of CHARGE syndrome and enable appropriate health guidance and genetic counselling." (PMID 26411921, 2015). "The mutational spectrum of CHD7 in patients affected by CHARGE syndrome is variable, including nonsense, frameshift, splice site and missense mutations, deletions and genomic rearrangements." (PMID 26334530, 2015). "CHARGE syndrome is a rare human disorder caused by mutations in the gene encoding chromodomain helicase DNA binding protein 7 (CHD7)." (PMID 24840056, 2014). "Heterozygous mutations in CHD7 are found in more than 60% of the patients with typical CHARGE syndrome, a multisystem autosomal-dominant or sporadic disorder including coloboma, heart anomalies, choanal atresia, retardation, genital, and ear anomalies." (PMID 25254043, 2014). "CHD7 haploinsufficiency causes CHARGE syndrome, the most consistent clinical feature associated with CHARGE is inner ear defects, including semicircular canal dysplasia that typically affects all three canals, and a Mondini form of cochlear hypoplasia." (PMID 25750614, 2014).
CHARGE syndrome (continued). "Single-gene deletions, for example, involving CHD7 are known to cause CHARGE syndrome associated with genital abnormalities and putatively associated with ASD." (PMID 24625521, 2014). "These pathogenic variants of CHD7 result in CHARGE syndrome, a complex disease characterised by variable presentation of a range of developmental defects." (PMID 24840056, 2014). "CHARGE syndrome patients exhibited mutations in the Chd7 gene, the product of which acts as a Sox2 transcriptional cofactor." (PMID 25309446, 2014). "Haploinsufficiency of CHD7 is associated with CHARGE syndrome, an autosomal dominant disorder characterized by multiple developmental symptoms that include hypotonia, limb abnormalities, and cranial nerve defects." (PMID 25412171, 2014). "These include the genes KAL1, FGFR1, FGF8 which encodes the ligand of FGFR1, PROKR2 and PROK2, NELF (nasal embryonic factor) and mutations in CHD7 associated with the CHARGE syndrome." (PMID 24204987, 2013). "Mutations in CHD7 are the major cause of CHARGE syndrome, an autosomal dominant disorder with an estimated prevalence of 1/15,000." (PMID 24368733, 2013). "Depending on the clinical selection, 60–90% of the individuals suspected for CHARGE syndrome have de novo, heterozygous mutations in the CHD7 (Chromodomain helicase DNA-binding protein 7, MIM#608892) gene." (PMID 24368733, 2013). "Most cases of CHARGE syndrome can be related to a mutation in the gene that encodes CHD7, a protein that is involved in remodelling chromatin." (PMID 24368735, 2013). "Loss of function of Chd7 resulted in several morphological defects similar to those observed in patients with CHARGE syndrome." (PMID 22363697, 2012). "A CHD7 mutation is found in >70% of patients with CHARGE syndrome (coloboma, heart defect, atresia choanae, retarded growth and development, genital hypoplasia, ear anomalies/deafness) and in ∼5% of KS patients." (PMID 22724017, 2012). "Mutations in the CHD7 gene are the major cause of CHARGE syndrome (OMIM 214800), an autosomal dominant congenital malformation disorder characterized by the combination of eye, ear, craniofacial structure, and heart defects." (PMID 23285124, 2012). "Here we present a novel mouse model for CHARGE syndrome with a spontaneous deletion mutation in the Chd7 gene." (PMID 22539951, 2012). "Although there is clear evidence that mutations in CHD7 gene are causative in CHARGE syndrome, the pathogenic mechanisms elicited by these mutations that lead to organs and systems dysfunction are not fully understood." (PMID 22363697, 2012). "Loss of function mutations in CHD7 lead to CHARGE syndrome, a well known malformation syndrome affecting several organs and sensory systems." (PMID 23285124, 2012). "Although most commonly due to mutations involving the chromodomain helicase DNA-binding protein-7, CHARGE syndrome can be caused by mutations in the SEMA3E gene." (PMID 22912587, 2012). "CHARGE syndrome patients often have microphthalmia and here we found that loss of function of Chd7 in zebrafish resulted in a small eye phenotype." (PMID 22363697, 2012). "These defects are similar to the major congenital anomalies associated with human CHD7 mutations in CHARGE syndrome." (PMID 22363697, 2012). "Approximately 60–70% of patients clinically diagnosed as CHARGE syndrome were found to have pathogenic mutations in the CHD7 gene." (PMID 21931733, 2011). "An auditory-vestibular phenotype approximating that of Twirler and Chd7 mutant mice is also observed in human patients with CHARGE syndrome and mutations of the human CHD7 gene." (PMID 21980308, 2011). "Five novel mutations and three previously reported mutations of the CHD7 gene was identified in Korean patients with CHARGE syndrome presenting with profound hearing loss and typical inner ear anomalies." (PMID 21931733, 2011). "This study presents another familial case of CHARGE syndrome in which a sib-pair carried the same frameshift mutation causing truncation of the CHD7 gene." (PMID 21931733, 2011).
CHARGE syndrome (continued). "Since CHARGE syndrome is a clinically complex disorder, mutational analysis of the CHD7 gene allows molecular confirmation of the diagnosis and also enables inclusion of mildly affected patients showing only few clinical features of CHARGE syndrome." (PMID 21931733, 2011). "As Verloes has emphasized, we believe that complete aplasia of the semicircular canals is a very specific finding that strongly suggests the presence of CHD7 mutations even if other characteristic signs of CHARGE syndrome are missing." (PMID 21931733, 2011). "Five of 9 patients were clinically diagnosed as atypical CHARGE syndrome but demonstrated various mutations of the CHD7 gene." (PMID 21931733, 2011). "De novo mutation of CHD7 is a major cause of CHARGE syndrome, a genetic condition characterized by multiple congenital anomalies." (PMID 20657823, 2010). "In humans, genetic mutations in CHD7 lead to CHARGE syndrome, a disorder characterized by multiple birth defects." (PMID 20657823, 2010). "CHD7 mutations have also been reported in patients diagnosed with diseases that have significant clinical overlap with CHARGE syndrome, including Kallmann syndrome (OMIM 147950), Omenn-like syndrome (OMIM 603554), and 22q11.2 deletion syndromes." (PMID 20657823, 2010). "Subsequent studies, identified pathogenic mutations in CHD7 in over 50% of a population of 110 individuals with CHARGE syndrome." (PMID 21532774, 2010). "De novo mutation of CHD7 is a major cause of CHARGE syndrome (OMIM 214800), a genetic condition characterized by multiple congenital anomalies." (PMID 20657823, 2010). "CHD7 is a human KIS homolog associated with CHARGE syndrome, a genetic disorder characterized by developmental retardation and complex abnormalities affecting several organs, including the brain and sensory systems." (PMID 20041201, 2009). "Mutations in CHD7, the human counterpart of kis, are associated with CHARGE syndrome, a developmental disorder affecting multiple tissues and organs." (PMID 18846226, 2008). "In a study of 110 patients it has been shown that cardiovascular malformations, coloboma and facial asymmetry are common findings in CHARGE syndrome caused by CHD7 mutation." (PMID 16959034, 2006). "Mutations in the CHD7 gene (member of the chromodomain helicase DNA protein family) are detected in over 75% of patients with CHARGE syndrome." (PMID 16959034, 2006). "The discovery of the CHD7 gene has led to the conclusion that most patients with CHARGE syndrome have a de novo autosomal dominant mutation." (PMID 16959034, 2006). "Previously, we showed that a patient who was compound heterozygous for a different combination of CDK9 variants [p.(A288T/R303C)] did exhibit a multiple malformation syndrome resembling CHARGE syndrome, a classic disorder featuring multiple malformations and caused by CHD7 variant." (PMID 40954203, 2026). "Mutations in the ATP-dependent chromatin modifier chromodomain helicase DNA-binding protein 7 gene (CHD7) have been identified as a major cause of CHARGE syndrome, with some studies suggesting an increase in Congenital Heart Disease prevalence in patients with pathogenic CHD7 variants." (PMID 40497996, 2025). "Our study also implicates that decreased CHD7 activity may prevent proper development and reduce the number of SGNs, leading to sensorineural hearing loss observed in patients with CHARGE syndrome." (PMID 40196636, 2025). "Consequently, it was less likely in our case; however, the phenotypic spectrum associated with variants in the chromodomain helicase DNA-binding protein 7 (CHD7) as the major cause of CHARGE syndrome has been broadened." (PMID 40989825, 2025). "One fetus with multiple anomalies was diagnosed with CHARGE syndrome prenatally (CHD7 variant)." (PMID 37535131, 2024). "Notably, a case study involving CHARGE syndrome highlights this complexity, where a Japanese patient with a frameshift mutation in the CHD7 gene developed PTCs." (PMID 39336755, 2024).
CHARGE syndrome (continued). "Similarly, while mutations in the chromodomains of zebrafish chd7 produce the morphological characteristics of CHARGE Syndrome including craniofacial defects, mutations in the ATPase domain do not." (PMID 38512854, 2024). "CHARGE syndrome results from aberrant neural crest development, affecting eye, heart, and facial structures, and has been attributed to pathogenic variants of the chromatin remodeler CHD7." (PMID 39418292, 2024). "However, CHD7 mutations in Kallmann syndrome are generally milder than those associated with CHARGE syndrome." (PMID 39596130, 2024). "All these reports suggested that patients with CHD7 variants may also present atypical CHARGE syndrome." (PMID 39285472, 2024). "Furthermore, we demonstrate features of Chd7 regulation are conserved in human, offering a potential resource for identifying pathogenic variants driving CHARGE syndrome as well as a novel mechanism for tissue specific activity of omnipresent factors." (PMID 39418292, 2024). "Lastly, the CHD7 gene is the major cause of CHARGE syndrome (coloboma, heart disease, atresia of the choanae, retarded growth and mental development, genitourinary malformations, and ear abnormalities), and we identified a novel variant, c.2594dupA (p.N866EfsX8), in one case." (PMID 39336818, 2024). "CHARGE syndrome is primarily caused by mutations in the chromatin remodeler-coding gene CHD7." (PMID 38477756, 2024). "Patients with syndromic congenital heart disease were screened out at enrolment, but mutations in CHD7 associated with CHARGE syndrome, KMT2D associated with Kabuki syndrome, NSD1 associated with Sotos syndrome, and PTPN11 associated with Noonan syndrome were identified in the study." (PMID 38339013, 2024). "Notably, CHD7 mutations are identified in approximately two-thirds of patients with CHARGE syndrome, and such mutations have been detected in some individuals with isolated CHDs." (PMID 38892128, 2024). "We postulated that some instances of CHARGE syndrome may be indirectly linked to CHD7, via perturbation of upstream regulatory mechanisms controlling CHD7 expression." (PMID 39418292, 2024). "The differential spatial expression of phox2ba in our zebrafish model of CHARGE syndrome suggests that, in addition to mutations in CHD7, there may be differences in the expression of other genes involved in regulating neural crest development." (PMID 37239446, 2023). "Thus, our study demonstrates that chd7 is critical to oligodendrocyte migration and myelination during early development in zebrafish and describes a mechanism potentially associated with CHARGE syndrome." (PMID 37686337, 2023). "Coloboma, heart defect, atresia choanae, retardation of growth and development, genital hypoplasia and ear anomalies/deafness (CHARGE) syndrome is most often associated with a mutation in CHD7, with 60–70% of patients with CHARGE syndrome having an autosomal dominant mutation in CHD7." (PMID 36648576, 2023). "Indeed the variable penetrance and expressivity of the signs associated with CHD7 variants both within and between families has been well-documented, in particular when missense variants are involved and a milder phenotype of CHARGE syndrome is seen." (PMID 37668839, 2023). "CHD7 (MIM:608892) pathogenic variants are a common cause of CHARGE syndrome." (PMID 37668839, 2023). "CHD7, an encoding ATP-dependent chromodomain helicase DNA-binding protein 7, has been identified as the causative gene involved in CHARGE syndrome (Coloboma of the eye, Heart defects, Atresia choanae, Retardation of growth and/or development, Genital abnormalities and Ear abnormalities)." (PMID 37686337, 2023). "Lastly, CHD7, a chromatin remodeling protein that exposes genes for transcription, has been shown to cause CHARGE syndrome, which has an associated retinopathy and is, in part, attributed to the loss of the genes downstream of CHD7′s function (i.e., genes located in the remodeled chromatin)." (PMID 36830640, 2023).
CHARGE syndrome (continued). "Thus far, only two cases of CHARGE syndrome combined with JBTS caused by CHD7 variant have been reported." (PMID 37547106, 2023). "Genetic causes for the uSNHL were found in 28% of subjects (5/18) including CHARGE syndrome (CHD7), autosomal recessive non-syndromic hearing loss (GJB2), Townes–Brocks syndrome (SALL1), Pendred Syndrome (SLC26A4) and Chromosome 8P inverted duplication and deletion syndrome." (PMID 36675424, 2023). "Some of these may include CHD7 causing CHARGE syndrome (MIM #214800), CHD4 as causative of Sifrim–Hitz–Weiss syndrome (MIM #603277), or CHD8 causing autism spectrum disorder (MIM #610528)." (PMID 37761804, 2023). "CHD7 haploinsufficiency is a major cause of CHARGE syndrome, a genetic disorder occurring with a prevalence of approximately 1 in 10 000 live births and characterized by malformations of the peripheral nervous system, craniofacial structures, eyes, ears, and heart." (PMID 35789070, 2022). "CHARGE syndrome (CS) (Online Mendelian Inheritance in Man [OMIM]# 214800) is a rare hereditary congenital anomaly with autosomal dominant transmission caused by the mutation of the chromodomain helicase DNA-binding protein 7 (CHD7) gene (OMIM# 608892)." (PMID 35938004, 2022). "The mutation of CHD7 is the main cause of CHARGE syndrome, but its function and mechanism in skeletal system remain unclear." (PMID 35418650, 2022). "Among the 12 patients with CHD7 variants, only 1 patient (8.3%) was diagnosed with CHARGE syndrome." (PMID 35669683, 2022). "Our data support previous proposals that CHD7 plays a key role in regulating the expression of genes needed for appropriate differentiation, which, when misregulated, might contribute to CHARGE syndrome when CHD7 function is impaired by mutation." (PMID 34663690, 2022). "The CHD7 helicase gene has been implicated in CHARGE syndrome, which is characterized by multiple symptoms, including atresia of the choanae, cranial nerve palsies, ear malformations, genital anomalies, intellectual disability, olfactory defects, and retarded growth." (PMID 36032672, 2022). "CHD7 is chromatin remodeler and mutations of CHD7 are the main cause of CHARGE syndrome." (PMID 35418650, 2022). "Mutations in CHD7 are identified in >75% of patients with CHARGE syndrome." (PMID 34231173, 2022). "Mutation of CHD7 is the main cause of CHARGE syndrome, a kind of developmental disorder involving multiple organ system defects, characterized as coloboma of the eye, heart defects, atresia of the choanae, retarded growth, genital anomalies, ear malformations and deafness." (PMID 35418650, 2022). "Further exploration of CHD7 function through gene expression studies may advance our understanding of Genotype-Phenotype Associations and the pathogenesis of CHARGE syndrome." (PMID 36045324, 2022). "CHD7 has been found mutated in two-thirds of patients with CHARGE syndrome." (PMID 36568983, 2022). "Mutations of CHD7 were identified in patients with CHARGE syndrome, KS, and CHH." (PMID 34231173, 2022). "CHARGE syndrome is a rare autosomal dominant disease caused by CHD7 gene mutations." (PMID 34297504, 2021). "CHD7 has been implicated in numerous developmental disorders including CHARGE syndrome and ASD." (PMID 33948885, 2021). "CHD7 was originally identified as the causative gene in CHARGE syndrome." (PMID 34563184, 2021). "In addition, SEMA3E mutations have also been reported in a single CHARGE syndrome patient, supporting the possible genetic interactions between semaphorins and CHD7, the main gene mutated in CHARGE syndrome." (PMID 34502334, 2021). "Most common amongst these are mutations in CHD7, causing CHARGE syndrome and maternal diabetes." (PMID 33257998, 2021). "CHARGE syndrome that affects cerebellar development can be caused by haploinsufficiency of the chromatin remodeling enzyme CHD7; however the precise role of CHD7 remains unknown." (PMID 34588434, 2021).